CXCL12 (C-X-C motif chemokine ligand 12)
Diseases named in the same sentence as CXCL12 in open-access papers (continued):
Sharing a sentence is not in itself a finding about the gene and the disease.
liver fibrosis (24 papers, 2006 to 2025). "Cxcl12 is a gene encoding a chemokine modulating the progression of liver fibrosis through its action on hepatic stellate cells, while Gjb1 encodes a gap junction membrane channel protein which plays an important role in the regulation of signal transfer and growth control in the liver." (PMID 21864415, 2011). "In conclusion, our study reveals that ALB inhibits inflammation and improves liver fibrosis by targeting the CXCL12/CXCR4 axis in CCl4-induced mice." (PMID 40371331, 2025). "AMD3100 can cut off the migration of inflammatory cells to the liver to impede the development of inflammation and inhibit the CXCL12/CXCR4 biological axis in liver fibrosis to protect against the activation of HSCs." (PMID 40002899, 2025). "In this study, we found that ALB effectively mitigates liver fibrosis by modulating the CXCL12/CXCR4 axis, thereby inhibiting the expression of profibrotic markers and reducing inflammatory responses." (PMID 40371331, 2025). "CXCL12/CXCR4 interactions are involved in immune cell migration and have been associated with liver fibrosis and cirrhosis progression." (PMID 41223189, 2025). "The chemokine CXCL12, also known as stromal cell-derived factor 1 (SDF-1), has numerous functions in the liver and is significantly upregulated in liver fibrosis." (PMID 38360740, 2024). "The CXCL12/CXCR4 (a CXCL12 receptor) axis modulates liver fibrosis by promoting the activation and the proliferation of the HSCs." (PMID 38360740, 2024). "Several studies have shown that the CXCL12 pathway is involved in the progression of chronic liver disease and liver fibrosis." (PMID 38767772, 2024). "ICG-001 suppres stromal CXCL12 suggests a potential therapeutic approach targeting activated HSCs in liver fibrosis." (PMID 39359922, 2024). "The CXCR4 ligand CXCL12 has previously been shown to have a potentially protective role during hepatic fibrosis through the expansion of hepatic progenitor and oval cells, which are beneficial for liver regeneration." (PMID 35336043, 2022). "CXCL12/CXCR4 is also known to activate the ERK1/2 cascade to induce the proliferation of HSCs in liver fibrosis." (PMID 35336043, 2022). "In vitro and in vivo studies have found that the inhibition of the CXCL12/CXCR4 biological axis in liver fibrosis can protect against the activation and migration of HSCs, and thus attenuates liver fibrosis." (PMID 34386499, 2021). "CXCL12 activates CXC chemokine receptor 4 (CXCR4) resulting in liver fibrosis, tumor growth, and HCC metastasis." (PMID 30034633, 2018). "Over expression of TIMP-1 is associated whit liver fibrosis, while MMP-13 cleaves and inactivates CCL2, CCL7 and CXCL12 leading to reduction in chemotaxis, as well as to a decrease in the fibrosis process." (PMID 29040281, 2017). "Taken together, our results showed little evidence for a key pathological role of signaling via the CXCL12/CXCR4 axis in either the BLM-induced PF model or the CCl4-induced hepatic fibrosis model." (PMID 26998906, 2016). "Interestingly, we discovered that ALB not only inhibits inflammation to improve liver fibrosis by targeting the CXCL12/CXCR4 axis, but also synergizes with MET to inhibit the progression of liver fibrosis." (PMID 40371331, 2025). "Moreover, CXCL12/CXCR4 also participates in the occurrence of liver fibrosis by promoting the activation and proliferation of hepatic stellate cells." (PMID 40002899, 2025). "At day 7 and 28 of the liver fibrosis model, CCl4 treatment tended to increase plasma CXCL12." (PMID 35562519, 2022). "In a mouse model of CCl4-induced liver fibrosis, the CXCL12/CXCR4 pathway is a critical chemotactic axis regulating the migration of MSCs from the bone marrow to the fibrotic liver, and recruited MSCs play different roles, including aggravating liver fibrosis and attenuating liver injury." (PMID 34386499, 2021).
liver fibrosis (continued). "In contrast, transplanted CXCR4-positive expanded endothelial progenitor cells (EPCs), induced by CXCL12 into the rat liver portal tracts, fibrous septa and hepatic sinusoids, effectively promote the remodeling of damaged tissues of liver fibrosis and suppress liver fibrogenesis." (PMID 34386499, 2021). "Thus, it is necessary to adopt more cell types, combined with targeted delivery or specific strategies to modulate the CXCL12/CXCR4 signaling to target this pathway in liver fibrosis." (PMID 34386499, 2021). "CXCL12 is expressed in bile duct epithelial cells in normal human liver and its expression is upregulated in the liver and plasma of patients with advanced hepatic fibrosis relative to control patients." (PMID 26998906, 2016). "Chemokines in the liver (Cxcl4 and Cxcl12) may modulate the progression of liver fibrosis through their actions on hepatic stellate cells." (PMID 17118137, 2006). "Furthermore, the study found that AS-IV may further exert its anti-HSC activation and anti-liver fibrosis effects through by regulating the C-X-C motif chemokine ligand 12 (CXCL12)/C-X-C chemokine receptor type 4 (CXCR4) signaling axis." (PMID 40337517, 2025). "Furthermore, the fact that the ACKR3 agonist compound 18a increased the bioavailability of CXCL12 (which can act as an agonist on the CXCR4 receptor) may even have counterbalanced the beneficial effect on liver fibrosis." (PMID 35562519, 2022). "The research results on the mechanism of action indicated thatthe combination therapysignificantly downregulate the expression levels of key proteins CXCL12 and CXCR4 in a mouse model of liver fibrosis." (PMID 40371331, 2025). "The CXCL12/CXCR4/CXCR7 chemokine axis is well known to regulate cell migration and is involved in the regulation of liver fibrosis." (PMID 38360740, 2024). "Here, the expression levels of CXCL12 and CXCR4 are significantly elevated in liver fibrosis and cirrhosis." (PMID 34386499, 2021). "Among these SHP regulated genes the chemokine CXCL12, together with its primary receptor CXCR4, play a major role during the progression of liver fibrosis by promoting hepatic stellate cell activation and contraction." (PMID 28117422, 2017). "Further, CXCL12 induces HSC proliferation and subsequent production of collagen I. In the current study, we evaluated AMD070, an orally bioavailable inhibitor of CXCL12/CXCR4 in alleviating BLM-induced pulmonary and CCl4-induced hepatic fibrosis in mice." (PMID 26998906, 2016). "The results revealed that effective suppression of the CXCL12/CXCR4 axis and Notch pathway through AMD3100-assisted siRNA therapy is promising for the inhibition of macrophage migration to inflammatory sites, thereby preventing hepatic fibrosis and alleviating MASLD." (PMID 40002899, 2025). "Recent studies have indicated that inhibiting the CXCL12/CXCR4 axis does not improve liver fibrosis and may even worsen it." (PMID 38360740, 2024). "However, simply blocking profibrotic CXCL12/CXCR4 axis is not sufficient to ameliorate liver fibrosis in vivo." (PMID 34386499, 2021).
thyroid cancer (24 papers, 2013 to 2025). "In canine lung adenocarcinoma and thyroid carcinoma, stromal T cell density was higher than in tumor regions, especially in cases with high CXCL12 expression scores." (PMID 40849508, 2025). "The CXCL12 expression score for thyroid carcinoma and renal cell carcinoma tended to be higher than that for other tumors." (PMID 40849508, 2025). "It was observed that high expression of CXCL12/CXCR4 and low density of CD8-positive T-lymphocytes are more likely to cause shorter overall survival in thyroid cancer." (PMID 36612163, 2022). "Here, senescent cells enhanced anoikis resistance in thyroid cancer cell lines via CXCL12/CXCR4 signalling." (PMID 28489070, 2017). "In addition, CAFs can synthesize and secrete CXCL12, which is a strong inflammatory factor, improving thyroid cancer cell proliferation, migration and invasion." (PMID 36077709, 2022). "Furthermore, the expression of several genes, such as GRIM-19, CXCL12, and PAK4, is associated with not only the development of thyroid cancer but also the pathogenesis of adenomyosis." (PMID 29522577, 2018). "The CXCL12/CXCR4/CXCR7 axis may contribute to thyroid cancer development by regulating cancer cell migration and invasion via AKT, ERK signaling and MMP-2 activation." (PMID 28272462, 2017). "CXCL12 binds to CXCR4 and CXCR7 proteins on thyroid cancer cells and activates several signaling pathways such as mTOR, ERK1/2, SAPK/JNK, Akt, p38, and BTK." (PMID 40136652, 2025). "In particular, CXCL12 (also known as SDF-1) binds to CXCR4 and CXCR7 proteins on thyroid cancer cells and consequently activates multiple signaling pathways, including mTOR, ERK1/2, SAPK/JNK, Akt, p38 and BTK." (PMID 36077709, 2022). "In thyroid carcinoma, miR-101 targets the CXCL12 (C-X-C motif chemokine ligand 12, stromal cell-derived factor 1)-mediated AKT and SNAIL signaling pathways to inhibit invasion and the EMT-associated signaling pathways." (PMID 31947678, 2020). "At present, CCL2, CCL15, CCL20, CXCL1, CXCL8, CXCL12, and CXCL16 are the main chemokines showing a role in thyroid cancer." (PMID 29977225, 2018). "miR-1 is able to inhibit thyroid carcinoma cell proliferation and migration by targeting CCND2, CXCR4 and CXCL12." (PMID 24079748, 2013). "The expression of CXCL12, CXCR4, and CXCR7 was detected in thyroid cancer tissue specimens." (PMID 29977225, 2018). "In the other two cancer types (particularly thyroid cancer) the CXCL12 gene was not included in the analysis because the change in the expression level of CXCL12 was slightly below our threshold (-0.0996)." (PMID 28178311, 2017). "To determine whether senescent cells were capable of attracting cancer cells through the CXCL12/CXCR4 signalling, we performed an in vitro cell migration assay using two kinds of thyroid cancer cell lines: SNU790-CXCR4 and HTH83." (PMID 28489070, 2017). "Therefore, therapies targeting the CXCL12/CXCR4/CXCR7 axis could be a promising and effective therapeutic strategy for thyroid cancer." (PMID 40136652, 2025). "Furthermore, by integrating analyses, we also directly verified the CXCL12 dominance in the HT-derived stromal cells, rather than cells from normal tissue or HT-free thyroid cancer samples." (PMID 38478516, 2024). "It was recently reported that in advanced CD8 negative thyroid cancer, high expression of CXCR4 and its ligand CXCL12 (SDF-1) correlates with bad prognosis, thus contradicting to TCGA data." (PMID 37006265, 2023).
endometriosis (23 papers, 2015 to 2026). The growth of functional endometrial tissue in anatomic sites outside the uterine body. "Loss of CXCR4, the receptor for CXCL12, in response to OCPs is also interesting, as this has been reported to reduce proliferation and lesion number in endometriosis." (PMID 38999962, 2024). "The expression of CXCL12 in endometriosis pathological tissues coupled with its increased presence in the systemic circulation of affected patients significantly contributes to the underlying pathology of endometriosis." (PMID 38115253, 2023). "Investigations revealed that CXCL12 is expressed four to six times more frequently in endometriosis lesions than in eutopic endometrium." (PMID 39021822, 2024). "CXCL12 was confirmed to enhance pregnancy rates in endometriosis mouse model, considered as a potential agent for therapy of endometriosis." (PMID 37393391, 2023). "CXCR4 is capable of forming dimers with MIF-bound CD74; however, the majority of the studies which have evaluated CXCR4 in the context of endometriosis have been evaluating it as a receptor for CXCL12." (PMID 35885004, 2022). "In order to further validate the expression of AGTR1 in EC and EU and to evaluate the diagnostic value of CXCL12, PTGER3, and AGTR1 in endometriosis, we need to increase the sample size." (PMID 36524127, 2022). "With the exception of CXCL12, all enriched genes were downregulated in CCs from patients with endometriosis." (PMID 35388025, 2022). "These pathways are related to immunity, and, except for CXCL12, all enriched genes are downregulated in endometriosis CCs." (PMID 35388025, 2022). "We further investigated the expression of E-cadherin (CDH1) and CXCL12 in endometriosis or control tissues by IHC." (PMID 32439908, 2020). "IHC confirmed the down-regulation of E-cadherin (CDH1) and up-regulation of CXCL12 in endometriosis tissues." (PMID 32439908, 2020). "E-cadherin was significantly down-regulated in endometriosis (P value = 0.028), while CXCL12 was significantly increased in endometriosis (P value = 0.015)." (PMID 32439908, 2020). "Through IHC, we confirmed that CXCL12 is significantly increased in endometriosis, accompanied by a decrease in the expression E-cadherin (CDH1), which is consistent with bioinformatics analysis." (PMID 32439908, 2020). "In a similar manner, AMD3100 also blocks chemoattraction of bone marrow stem cells to CXCL12 produced by endometriosis." (PMID 31904910, 2020). "In the mammalian reproductive system, chemokines are often involved in multimodal events closely related to the establishment, maintenance, and regression of fertility, It has been shown that Uterine injection of CXCL12 increased the pregnancy rates in a mouse model of endometriosis." (PMID 40211853, 2026). "The local recruitment of uNK cells involves cytokines and chemokines such as IL-15 and C-X-C motif chemokine ligand 12 (CXCL12), and aberrant expression of these molecules in endometriosis may further impair uNK accumulation within the endometrium." (PMID 41009686, 2025). "In addition, CXCL12 regulates the aggregation of white blood cells into the abdominal cavity and tissue growth in endometriosis, and 35 miRNAs expression changes were found in endometrial stromal cells treated with CXCL12." (PMID 40838210, 2025). "Additionally, CXCL12/CXCR4/CXCR7 recruit and facilitate stem cell homing from the circulation to the endometriosis, causing inflammation." (PMID 41009445, 2025). "However, the importance of mesenchymal stem cells, which are recruited by endometriosis lesions using the C-X-C motif chemokine ligand 12/14 (CXCL12/CXCR14) signaling pathway, is currently under discussion." (PMID 39021822, 2024). "Interestingly, all enriched genes underwent a negative regulation of expression in the CCs of the patients with endometriosis I/II compared to the controls, except for the CXCL12, which was up-regulated." (PMID 35388025, 2022).
endometriosis (continued). "The high expression of CXCL12 in endometriosis and expression of CXCR4 and CXCR7 in BMDCs suggested that CXCL12 might serve to regulate BMDCs trafficking towards endometriosis." (PMID 31904910, 2020). "In endometriosis, it is still unclear whether CXCL12 promotes EMT through the CXCL12-CXCR4 axis or the CXCL12-CXCR7 axis." (PMID 32439908, 2020). "Elimination of local endometrial CXCL12 suggests that the effect of AMD3100 in blocking CXCL12 is not a direct effect endometrial cells; rather, bone marrow cell mobilization and recruitment to endometriosis is likely mediated by systemic CXCL12 and the impact on bone marrow‐derived cells." (PMID 31904910, 2020). "A number of mechanisms may explain the increased CXCL12 production and stem cell recruitment in endometriosis." (PMID 31904910, 2020). "Blocking CXCL12 activity on its receptor greatly reduced BMDCs engraftment in endometriosis." (PMID 31904910, 2020). "The identification of CXCL12 as the primary chemokine that recruits BM-derived cells to the uterus may allow therapeutic use in endometriosis and other uterine disease to restore fertility." (PMID 25957946, 2015). "PPI analysis showed that CXCL12 interacts directly with complement C3 and C-C motif chemokine ligand 21 (CCL21), and a previous study showede CCL21 is up-regulated in endometriosis, which acts through inflammatory responses." (PMID 32439908, 2020). "Our results indicate lower CXCL12 expression in EAOC patients, distinct from endometriosis." (PMID 40166682, 2025). "Suppressing the CXCL8 and CXCL12/CXCR4/CXCR7 axis prevents the development of inflammation in both PCOS and endometriosis, which may help to improve the prognosis of disorders associated with inflammation." (PMID 41009445, 2025). "To assure that the effects of treatment was due to blockade of BMDC recruitment and not local effects of endometrial cell‐derived CXCL12, we repeated these experiments creating endometriosis derived from uterine‐specific CXCL12 null mice." (PMID 31904910, 2020). "Endometriosis lesion size was not effected when the local effects of CXCL12 were abrogated using uterine‐specific CXCL12 null mice, suggesting an effect primarily on bone marrow cell migration rather than a direct endometrial effect." (PMID 31904910, 2020). "In this unbiased study, we found EMT in endometriosis could be potentially induced by inflammatory cytokines such as C-X-C motif chemokine ligand 12 (CXCL12), also known as stromal cell-derived factor 1 (SDF1)." (PMID 32439908, 2020). "Given the central role of the CXCL12/CXCR4/CXCR7 axis on BMDCs trafficking and in the pathogenesis of endometriosis, we hypothesized that blocking CXCR4 or CXCR7 in endometriosis using a reproductive and immune‐competent murine model would inhibit the growth of endometriosis." (PMID 31904910, 2020). "Studies have found that CXCL12/CXCR4/CXCR7 axis mainly promotes the proliferation, migration, and invasion of endometriotic foci through mechanisms such as angiogenesis and induction of stem cell migration In endometriosis, and this process may be regulated by estradiol." (PMID 36524127, 2022).
neuroblastoma (23 papers, 2007 to 2023). Neuroblastoma (NB) is the most common solid, extracranial childhood tumor. "This suggests possible involvement of factors other than CXCL12 in the increased MMP-9 secretion and invasiveness associated with neuroblastoma cells in the presence of MSC secretome." (PMID 25774696, 2015). "Both CXCL12 and CXCR4 expression have been associated with tumorigenesis in many cancers including breast, ovarian, renal, prostate, and neuroblastoma." (PMID 20376365, 2010). "Therefore, additional investigations would be necessary to better understand the role of CXCR4—CXCL12 axis in neuroblastoma biology." (PMID 25774696, 2015). "In addition, we demonstrated that NB cells, upon in vitro incubation with MSCs, acquired a more invasive behavior towards the bone marrow, i.e. the primary site of neuroblastoma metastases, and to CXCL12 which is highly expressed by bone marrow and NB cells." (PMID 23119082, 2012). "Moreover, significant reduction in tumor size and complete remission have been observed with CCR2b-GD2-CAR T cells and CXCR4-EGFRvIII-CAR NK cells infused in mice bearing CCL2 producing GD2 neuroblastoma or CXCL12 secreting EGFRvIII glioblastoma cells, respectively." (PMID 30420855, 2018). "Besides acting as a cofactor for HIV, CXCR4 mediates the CXCL12-directed migration of cancer cells to metastatic sites through the promotion of angiogenesis and migration of tumor cells in breast, lung, ovarian, renal, prostate and neuroblastoma." (PMID 20376365, 2010). "Presence of CXCL12 could be measured by ELISA in several nude mouse organs, and the highest levels of CXCL12 were found in the adrenal gland, the natural primary tumour microenvironment for neuroblastoma." (PMID 17925864, 2007). "Indeed, studies have found that MSCs isolated from neuroblastoma tumors carried transcriptomic profiles associated with EMT, which in turn were associated with poor prognosis, and expressed high levels of C-X-C Motif Chemokine Ligand 12 (CXCL12), promoting neuroblastoma metastasis and invasiveness." (PMID 33917501, 2021). "It has been reported that neuroblastoma cell lines express CXCR4 and bind the CXCR4 ligand stromal-derived factor-1 (SDF-1), also known as C-X-C motif chemokine 12 (CXCL12), which induces tumor cell migration." (PMID 30149659, 2018). "In neuroblastoma cell lines, overexpression of CXCR7 was shown to limit cell growth and CXCR4/CXCL12-mediated chemotaxis." (PMID 30420855, 2018).